CD86 (CD86 molecule)
Diseases named in the same sentence as CD86 in open-access papers (continued):
Sharing a sentence is not in itself a finding about the gene and the disease.
tumor (continued). "In addition, we demonstrated that, upon activation, NK cells could significantly increase the expression of CD86 both in vitro and in vivo, and ligation of CD86 with CTLA4Ig significantly increased the ability of NK cells to kill tumor cells." (PMID 24349559, 2013). "Furthermore, a human NK cell line that expressed high level of CD86 was directly activated by CTLA4Ig so that killing of tumor targets was enhanced; this enhanced killing could be inhibited by blocking CD86." (PMID 24349559, 2013). "Interestingly, it appears that this pharmacological treatment increases the immunogenicity of the tumor cells because it enhances the expression of the stimulatory CD86 molecules and it down regulates the IFN-γ-induced expression of the inhibitory molecule PD-1L." (PMID 20140259, 2010). "Upon DAMP recognition, DCs undergo significant upregulation of co-stimulatory molecules (CD80, CD86) and major histocompatibility complex (MHC) class II expression, enhancing their capacity for tumor antigen presentation." (PMID 41424843, 2026). "At the same time, miR-32-5p increases production of M1-type proinflammatory factors such as CD86, CCL2, tumor necrosis factor-α (TNF-α), and interleukin-6 (IL-6), thereby enabling macrophage polarization toward tumor-suppressive phenotype." (PMID 41608526, 2026). "In vivo, B. lactis V9 alone moderately inhibited tumor growth but synergized with αPD-1 to achieve a 50% tumor growth inhibition and extend survival in CT26 models, accompanied by increased IFN-γ+CD8+ T cells and activated CD86+CD11c+ dendritic cells." (PMID 42273689, 2026). "Strikingly, exposure to NETs‐containing supernatant derived from PUS7‐overexpressing tumour cells robustly induced M2‐like macrophage polarization, as evidenced by a significantly increased CD206/CD86 ratio." (PMID 41496500, 2026). "Tumor-infiltrating macrophages also showed higher CD206 (M2 marker) and PD-L1 expression, with a concomitant reduction in CD86 (M1 marker) expression." (PMID 41545338, 2026). "Future investigations should characterize macrophage subsets (such as iNOS/CD86 versus Arg1/CD206) using flow cytometry or multiplex immunostaining to determine whether macrophage-derived cytokines contribute to IL-6/STAT3 signaling during UVB-driven tumor promotion." (PMID 41596287, 2026). "Consistent with the tumor responses, EGFR‐19del LLC tumors contain significantly lower numbers of CD11c+MHC‐II+ DCs, which express reduced levels of CD80 and CD86, than the WT tumors." (PMID 41144813, 2026). "Moreover, mature DCs (CD45+CD11c+CD80+CD86+) within the tumors were analyzed by flow cytometry after the third treatment, revealing a higher proportion in the MNs (TDEVs@OVs)‐treated group, indicative of enhanced recruitment and maturation of DCs crucial for activating tumor‐specific T cells." (PMID 41496440, 2026). "The protein levels of CD86 and CD8 in the tumour, as assessed by IHC, were significantly increased in the magnolol plus RT group." (PMID 40830825, 2025). "The expression patterns of CD68, CD86, and CD163 were first analyzed to assess differences between the tumor nest and tumor stroma." (PMID 40510346, 2025). "Blocking TREM2 signaling promotes cross-presentation of tumor antigens, boosts CD80/CD86 levels, and synergizes with anti–PD-1 therapy to control tumor growth." (PMID 40821795, 2025). "During tumor elimination, the interaction of CD80 and CD86 on antigen-presenting cells with CD28 on T cells regulates T-cell activation, thereby initiating T-cell proliferation." (PMID 40343258, 2025). "Among the tumors injected with IFNβ-LNPs, TAMs displayed lower levels of the immunosuppressive M2 macrophage marker, CD206, along with increases in the anti-tumor M1 macrophage markers, CD80 and CD86." (PMID 40006725, 2025).
tumor (continued). "On the contrary, immature neutrophils (CD10- CD16-), PMN-MDSC, PD-L1+ M-MDSC, and PD-L1+ e-MDSC, pDC expressing ICOS-L, CD86, or CD40 as well as CD16- NK cell proportions with limited antitumoral potential dominated in tumor tissues." (PMID 41221283, 2025). "Compared with A41L-intact VVLΔTKΔN1L, the infiltration of CD4+ T and natural killer (NK) cells in TME and the proportion of dendritic cell (DC), activated DC, CD86+ DC and CD8+ T cells in tumor tissues increased." (PMID 40350204, 2025). "Our study revealed a correlation between MMP14 expression and various molecules regulating tumor immune cells, including CSF1R, HAVCR2, KDR, PDCD1LG2, TGFB1, CD70, CD86, and CXCL1." (PMID 40352589, 2025). "Furthermore, another study showed that butyrate inhibited the upregulation of CD80/CD86 on dendritic cells and the expression of Inducible T-cell Co-Stimulator on T cells in a mouse model, thereby impairing the recruitment of effector and memory T cells targeting tumor antigens." (PMID 40771692, 2025). "Within the tumor microenvironment (TME), CD86 binds to CD28 and CTLA-4 on the surface of T cells, regulating T cell activation, proliferation, and survival." (PMID 41006647, 2025). "Specifically, the quadruple combination showed the strongest reprogramming effects, reducing M2 markers (CD206, CD163) and increasing M1 markers (CD86, CD11c, HLA-DR) in the indirect co-culture with HCT116 cells, suggesting a shift toward anti-tumor immunity." (PMID 40160820, 2025). "CD86, IL10RA, TNFSF13B, and CMKLR1 suppress effective anti-tumor immunity while simultaneously potentially promoting pro-tumor immune subsets – representing immunosuppressive signaling." (PMID 41006647, 2025). "The co-stimulatory molecules CD80 and CD86 were abundantly expressed on activated dendritic cells, whereas I-A/IE, an MHC-II molecule, was detected on DCs loaded with tumor antigens." (PMID 40386771, 2025). "M1 macrophages, known for their pro-inflammatory and anti-tumor functions, typically express markers such as CD80, CD86, and IL12." (PMID 41019045, 2025). "In line with in vitro findings, tumor-infiltrating cDC1s exhibited elevated expression levels of CD40, CD80, and CD86 following DS treatment." (PMID 40625660, 2025). "The most significant influence was observed for M1-like macrophages, for which the tumor cell medium alone strongly induced the expression of the costimulatory molecules CD80 and CD86, as well as MHC II." (PMID 40724825, 2025). "At 48 hours post-treatment, an elevation in anti-tumor macrophage activation markers was observed, with increases in expression of MHCII, co-stimulatory markers CD86 and CD80, PDL1 and the migratory marker CCR7." (PMID 41048107, 2025). "In Fgl2−/− mice, ovarian tumors displayed enhanced infiltration of cDC1s, CD3+ T cells, and DNAM-1+ NK cells, and they induced expression of co-stimulatory markers (MHC-II, CD86+, and CD40+) in spleen, resulting in reduced tumor burden." (PMID 41470247, 2025). "This study revealed progressively elevated CD163+ and CD86+ TAMs levels in colorectal tissues: normal mucosa < CRA < CRC, suggesting their potential involvement in immune modulation during tumor progression." (PMID 41395618, 2025). "Especially, a positive correlation between ACAA1 expression in tumor cells and six immune checkpoint-related genes, namely CD27, PDCD1, CD86, BTLA, TIGIT, and CD28, on immune cells within the tumor microenvironment." (PMID 41277949, 2025). "Complementary tissue immunofluorescence assays further demonstrated an upregulation of the M1 macrophage marker CD86 and a concurrent downregulation of the M2 marker CD163 in RP-6306-treated tumor tissues." (PMID 40664640, 2025). "TAMs contribute to T-cell dysfunction by expressing immunosuppressive molecules, such as CD80, CD86, and VISTA, which inhibit T-cell activation and impair the anti-tumor immunity." (PMID 40722951, 2025).
tumor (continued). "The proportions of mature dendritic cells (DCs, CD86+/MHC class II+), CD4+CD3+ T cells, and CD8+CD3+ T cells were significantly higher in both peripheral blood and tumor tissues from the RIVA‐660 nm group compared to control groups." (PMID 40619603, 2025). "This suppressed PI3Kγ signaling, reducing the expression of M2 markers (CD206 and IL-10) and increasing the expression of M1 markers (CD86 and TNF-α), which inhibited tumor growth by reprogramming TAMs in 4T1 and MC38 mouse models." (PMID 40850976, 2025). "TCMs co-cultured with B16-F10 tumor cells at a 1:10 ratio increased their relative expression of MHC1, MHC2, CD80, and CD86 over the course of 48 h as compared to TCMs cultured in medium alone." (PMID 41050935, 2025). "A significantly elevated expression of checkpoint inhibitors was detected in Cluster two tumours, including PD-1, PD-L1, CTLA4, CD80/CD86 costimulatory molecules, and emerging targets like TIGIT and LAG3." (PMID 41050056, 2025). "Tumor-bearing mouse brain tissues were fixed and sectioned for IHC staining of CD206 (M2 marker) and CD86 (M1 marker)." (PMID 39990664, 2025). "Treg cells can restrict the activity of antigen-presenting cells by downregulating the expression of CD80 and CD86 in a CTLA4-dependent way, therefore preventing the presentation of tumor antigens and the activation of tumor-specific T cells." (PMID 41019045, 2025). "IgE engagement of monocytes via the Fc region induced tumor cell cytotoxicity and a pro-inflammatory shift with upregulation of immune-stimulatory CD40, CD80 and CD86, and downregulation of scavenger CD163, cell surface molecules." (PMID 40074330, 2025). "As the most potent APCs in the body, DCs upregulate the expression of costimulatory molecules such as CD80, CD86, CD40, and the chemokine receptor CCR7 upon stimulation with tumor antigens." (PMID 40040692, 2025). "In the model, T cell activation occurs through the binding of TCR/CD3 complex to major histocompatibility complex (MHC) on APCs and tumor cells, accompanied by the physical interaction between CD80/CD86 on APCs and CD28 on T cells." (PMID 40276607, 2025). "The expression of antigen-presenting biomarker (MHCII+, CD86+, CD80+) on macrophages and DCs was significantly enhanced in tumors treated with CAR-Ms, compared to the Con-Ms group tumor, indicating enhanced maturation and antigen-presenting function." (PMID 40814015, 2025). "Further evaluation of the immune effects of ChS-Ce6-induced pyroptosis showed a significant increase in the proportion of CD80+CD86+ cells in tumor-draining lymph nodes and a markedly higher infiltration of CD4+ and CD8+ T cells in the tumor tissues." (PMID 40698137, 2025). "FGL2, primarily produced by tumor-infiltrating macrophages/monocytes and DCs, downregulates CD40 and CD86 on CD11+ DCs through FcγRIIB/III-mediated signaling." (PMID 41470247, 2025). "Overall, the transfer of immune stimulatory or regulatory molecules—CD80, CD86, OX40L, HLA-G, and PD-L1—via trogocytosis significantly inhibits anti-tumor immunity and contributes to the development of the immune-suppressive tumor microenvironment." (PMID 39741180, 2025). "Regarding the expression of additional surface proteins, especially tumor-infiltrated and to a lesser extent ascites-derived pDC expressed ICOS-L, CD86, and CD40 indicating higher pDC activity in OC tissue." (PMID 41221283, 2025). "It inhibited the M2-like polarized tumor-promoting phenotype of macrophages, as evidenced by a decrease in CD206 expression and an increase in CD86 expression in flow cytometry, as well as a decrease in ARG1 protein level in Western blot assays." (PMID 40430260, 2025). "Further, we co‐cultured LLC tumor cells with peritoneal macrophages at ratios of 1:1 and 3:1, stimulating them with CCM or CFM, respectively, and measured the expression levels of CD86, CD206, TNF‐α, and CXCL10." (PMID 40637137, 2025).
tumor (continued). "In the untreated tumor model, the proportion of CD206+ M2-type TAMs was high, while CD86+ M1-type TAMs were relatively low." (PMID 40697374, 2025). "The Wilcoxon test revealed a significant difference in the expression of the markers CD68, CD86, and CD163 between the tumor nest and tumor stroma in both the primary tumor and brain metastases across the overall cohort (p < 0.0001)." (PMID 40510346, 2025). "We assessed the expression of surface markers characteristic of both pro-inflammatory (CD86) and anti-inflammatory (CD163, CD206, CD209) phenotypes on macrophages cultured either in monocultures or in co-culture with tumor cells." (PMID 41009763, 2025). "Immune checkpoint blockade in melanoma models revealed that tumor-infiltrating lymphocyte efficacy strongly correlated with moDCs populations expressing elevated CD80, CD86, and MHC-II." (PMID 40924040, 2025). "In the tumor-draining lymph nodes (tdLNs), SAN-TLRa vaccination slightly increased the proportion of CD80+ and CD86+ DCs, while SAN-TLRa vaccination followed by BMAA treatment further enhanced the DC maturation." (PMID 40083927, 2025). "In a murine model, Ncom Gel markedly increased the percentage of CD80+ and CD86+ DCs in TDLNs, triggering an expansion of IFN-γ–producing CD8+ and CD4+ T cells and leading to a significant delay in tumor growth." (PMID 41294574, 2025). "In HPV-driven murine models, B cells exhibit dynamic immunomodulatory functions - accumulating in draining lymph nodes while downregulating MHC class II and CD86, yet upregulating PD-L1 and CD39 to suppress T-cell responses and facilitate tumor progression." (PMID 40808954, 2025). "Significantly, SAg-exposure enhanced inflammatory activation of CLL tumour cells, which acquired CD38, CD40, CD86, while downregulating CD27 (p≤0.005), even in cultures from ibrutinib-treated CLL patients." (PMID 40207214, 2025). "The elevated levels of CD40, CD86, and MHC-I confirmed the increased dendritic cell maturation and activation in PAK1KO tumours." (PMID 40943273, 2025). "M1 macrophages are usually recognized by the expression of CD86 and CD64 and by the production of CXCL9, which are indicative of their pro-inflammatory and anti-tumor activity." (PMID 39858472, 2025). "GO analysis, conducted across three categories (cellular component [CC], biological process [BP], and molecular function [MF]), further confirmed the enrichment of DEGs in anti‐tumor immune‐related pathways, including the JAK‐STAT pathway and CD86 synthesis." (PMID 40956367, 2025). "M1 macrophages are classical immune-activated macrophages that provide co-stimulatory signals through CD86, which binds to the CD28 receptor on T cells, leading to T cell activation and promoting anti-tumor immune responses." (PMID 40475760, 2025). "Comparing oncolysates from rVSV- and rVSV-NDV-infected tumor cells, we observed a significantly greater upregulation of MHC-I, MHC-II, and CD86 on DCs that had been co-cultured with oncolysates from syncytia-forming rVSV-NDV." (PMID 40896365, 2025). "We then investigated the anti-tumor immune responses by evaluating the expression levels of CD3+, CD4+, and CD8+ T cells, as well as DC maturation (CD11c+, CD86, and CD80) in tumors." (PMID 40234392, 2025). "This upregulation of CD80 and CD86 on macrophages suppresses anti-tumor immunity following radiation therapy, despite the known importance of CD80 and CD86 in conventional costimulation." (PMID 41417245, 2025). "The results show that combination therapy increase in local tumor infiltration with more mature CD86+ DCs, activated IFN-γ+CD8+ T cells and tumor antigen-specific T cells (gp70-tetramer+ CD8+ T cells) compared to the OVV or mNbTIM3 treated mice." (PMID 41291902, 2025).
tumor (continued). "After migrating to a tumor, they differentiate from SCL to an effector state, which requires costimulation by CD80 and CD86 of APC in the TME." (PMID 39835538, 2025). "For the immune part, we focused on the TCR-mediated signaling pathway and major immune checkpoints including PD-1, PD-L1, CD28, CD80/CD86, LAG3, CTLA4, TIGIT, CD155, OX40, OX40L, 4-1BB, and 4-1BBL (expressed on T cells, tumor cells, or APCs)." (PMID 40276607, 2025). "Lastly, as mTOR was overexpressed in DLBCL compared with control samples, we investigated its expression in CD86+ cells in DLBCL samples (intra-T vs peri-T) and in DLBCL vs non-tumor control (lymph nodes) samples." (PMID 41415285, 2025). "Specifically, responsive organoids (N = 6) showed low MSLN expression, and an abundance of cytotoxic CD8 + T-cells and tumor-suppressive TAM expressing high HLA-DR, CD86, and CXCL9." (PMID 41335396, 2025). "We demonstrate a mechanism of macrophage-driven immune suppression in the tumor environment post-RT via CD80 and CD86-mediated expansion of CD4 T cells and Treg." (PMID 41417245, 2025). "A comprehensive analysis of ICPs revealed significantly higher levels of ICPs such as CD44, CD80, CD86, and CTLA-4 in the high-TKT expression group, thereby allowing tumor cells to evade immune surveillance, and facilitating tumor progression." (PMID 40230848, 2025). "The proportion of CD45+CD11b+F4/80+CD206+CD86- cells (M2 macrophages or TAMs) was significantly lower in the PTX+SHP group compared to the PTX group, indicating a reduced infiltration of tumor-promoting macrophages." (PMID 40094005, 2025). "used immunofluorescent labeled antibodies against M1 and M2 macrophages (anti-CD86 and anti-CD206, respectively) and showed significantly higher amounts of M2 macrophages in F. nucleatum-positive tumor biopsies." (PMID 40895532, 2025). "IHC analysis further confirmed an M2‐biased tumour microenvironment, showing increased expression of CD206 and Arg‐1 alongside decreased CD86 and iNOS expression in LDHA‐overexpressing tumours." (PMID 41399129, 2025). "It inhibited the M2-like polarized tumor-promoting phenotype of macrophages, as evidenced by a decrease in CD206 expression and an increase in CD86 expression in flow cytometry, as well as a decrease in ARG1 protein levels in Western blot assays." (PMID 40430260, 2025). "In tumor IHC-stained tissue, the expression of CD8 and CD86 was elevated in the UMSC/miR-124-PD-1 and its derived exosomes group." (PMID 40134003, 2025). "Mature DCs express co-stimulatory molecules including CD80, CD86, CD40 and CD70, that enables DCs have the capacity to activate T cells and NK cells in tumor immune-surveillance, and directly kill tumor cells." (PMID 38554155, 2024). "Blockade of CD86 alone or in combination with PD-1 enhanced intratumoral CTL accumulation, and the combination significantly increased RT-induced tumor regression and OS." (PMID 38349740, 2024). "Co-culture with 3A1-transfected tumor cells also showed some increase in expression of CD80 and CD86." (PMID 39007281, 2024). "Manual gating confirmed these findings and showed that CD86 blockade in the context of RT increased the frequency of CD44+TCF-1– cells among CD8+ T cells in both the TdLN and tumor." (PMID 38349740, 2024). "Using immunofluorescence, F4/80 + CD86 (M1) and F4/80 + CD206 (M2) were double-stained and labeled to analyze the effect of inosine on M1 and M2-type macrophages in tumor tissues." (PMID 39795180, 2024). "This enables the tumor to evade immune detection by inhibiting inflammatory cytokines like TNF-α and suppressing MHC II, CD80, and CD86 expression." (PMID 39118076, 2024). "butyrate restrains anti-CTLA-4-induced up-regulation of CD80/CD86 on dendritic cells and ICOS on T cells, accumulation of tumor-specific T cells and memory T cells." (PMID 39351241, 2024).